SLC7A9 (solute carrier family 7 member 9)
Diseases named in the same sentence as SLC7A9 in open-access papers (continued):
Sharing a sentence is not in itself a finding about the gene and the disease.
cystinuria (continued). "A previous study of a cystinuria mouse model reported that most of their Slc7a9 −/− mice developed cystine stones, but still seven mice appeared non-lithiasic." (PMID 35416493, 2022). "Two patients diagnosed with cystinuria were tested for the genetic mutations SLC3A1 and SLC7A9, respectively." (PMID 35612621, 2022). "Cystinuria can be categorized into three types: SLC3A1 mutation is known as type A; SLC7A9 mutation is known as type B; both SLC3A1 and SLC7A9 mutations are known as type AB." (PMID 36421847, 2022). "•SLC7A9 Cystinuria gene was recently isolated in many cystinuria patient from different racial populations." (PMID 33680451, 2021). "The heterodimeric b0,+AT-rBAT transporter encoded by the SLC7A9 and SLC3A1 genes, is also known as “cystine transporter”, based on its association with cystinuria detailed further below." (PMID 33302555, 2020). "Inactivating mutations in the human SLC7A9 and SLC3A1 genes result in the partial failure of cationic amino acid reabsorption, clinically impressing as cystinuria." (PMID 33302555, 2020). "So far, two genes have been implicated in the genesis of cystinuria: Solute Carrier Family 3 Member 1 (SLC3A1) and Solute Carrier Family 7 Member 9 (SLC7A9)." (PMID 30450686, 2019). "Cystinuria is an inherited metabolic disease that is caused by defects in two genes, SLC3A1 and SLC7A9, which result in a renal reabsorptive defect of cystine and other dibasic amino acids, including ornithine, arginine, and lysine." (PMID 28166740, 2017). "We also compare these mutations that have been reported to cause cystinuria with the natural variation of SLC3A1 and SLC7A9 present in the large population study of genetic variation ExAC." (PMID 28812535, 2017). "For both genes, there is a clear difference in the distributions between the mutations known to be associated with cystinuria and the variants only found in ExAC (p = 1.69e-10 for SLC3A1, and p = 2.078e-06 for SLC7A9, Wilcoxon rank sum test)." (PMID 28812535, 2017). "Two genes, SLC3A1 and SLC7A9, coding respectively for rBAT and b0,+AT, account for the genetic basis of cystinuria." (PMID 28717662, 2017). "Cystinuria can be inherited in humans as an autosomal recessive (type IA and IB) and dominant (type IIA and IIB) trait due to SLC3A1 (IA and IIA) and SLC7A9 (IB and IIB) variants, respectively." (PMID 27404572, 2016). "In humans, dogs and mice, cystinuria is caused by variants in one of two genes, SLC3A1 and SLC7A9, which encode the rBAT and bo,+AT subunits of the bo,+ basic amino acid transporter system, respectively." (PMID 27404572, 2016). "Human cystinuria is genetically heterogeneous with 169 SLC3A1 (Type A) and 121 SLC7A9 (Type B) variants found thus far in human patients (HGMD database accessed on April 2016), respectively." (PMID 27404572, 2016). "Summarizing, generation and characterization of type AB cystinuria mouse model exhibited a digenic inheritance where 4% of double heterozygous mice (Slc7a9+/-Slc3a1+/-) present lithiasis phenotype." (PMID 26359869, 2015). "The lack of a genotype/phenotype correlation has led to propose a genetic classification for cystinuria defined as type A if mutations are found in SLC3A1, type B if mutations are found in SLC7A9 and type AB when one mutation is found in each gene." (PMID 26359869, 2015). "Tracking the lithiasic phenotype by X-ray allowed us to detect calculi formation in 4% of the double heterozygous mice (Slc7a9+/-Slc3a1+/-) demonstrating that cystinuria has a digenic inheritance pattern in this mouse model." (PMID 26359869, 2015). "Slc7a9 heterozygous mice are classified as non‐type I cystinuria which hyperexcretes cystine and dibasic amino acids but does not show lithiasic phenotype." (PMID 26359869, 2015). "Cystinuria caused by mutations in SLC3A1 (rBAT) has an autosomal recessive inheritance pattern (OMIM 600918) and mutations in SLC7A9 (b0,+AT) follows a partially autosomal dominant inheritance pattern (OMIM 220100)." (PMID 26359869, 2015).
cystinuria (continued). "So far, two genes responsible for cystinuria have been identified: SLC3A1 (chromosome 2p21) encodes the heavy subunit rBAT of a renal b0,+ transporter while SLC7A9 (chromosome 19q12) encodes its interacting light subunit b0,+AT." (PMID 22480232, 2012). "Cystinuria genes were identified 5 times (SLC7A9 and SLC3A1) in 5 patients (5%)." (PMID 40126616, 2025). "Cystinuria is well-suited for gene therapy, mainly because of the disease’s autosomal recessive nature and manageable gene sizes (SLC3A1 2.3 kb, SLC7A9 1.8 kb), also, the core of the pathogenic mechanisms is located in the proximal tubule, which is easily accessible." (PMID 40786091, 2025). "Four additional variants were excluded because they were associated with a mild condition, including stationary night blindness (GPR179, MIM #614565), mild cystinuria (SLC7A9, MIM #220100), postaxial polydactyly (IQCE, MIM# 617642) and pseudoxanthoma elasticum (ABCC6, MIM #264800)." (PMID 36978159, 2023). "To date, two genes have been identified to cause cystinuria: SLC3A1 and SLC7A9." (PMID 37893120, 2023). "Cystinuria can be caused by mutations in the SLC3A1 and/or SLC7A9 gene." (PMID 38114997, 2023). "Utilizing the molecular tools showed that genetic mutations of SLC3A1 were associated with type I cystinuria, while mutations of SLC7A9 were associated with non-type I cystinuria." (PMID 33680451, 2021). "Cystinuria is a metabolic disease caused by defects in the SLC3A1 and SLC7A9 genes." (PMID 32133030, 2020). "In 103 cystinuria patients, 83.5% had at least one SLC3A1 or SLC7A9 mutation." (PMID 30342472, 2018). "With the exclusion of SLC7A13/AGT1 as the third cystinuria gene accounting for the SLC3A1 and SLC7A9 mutation negative cases, it becomes obvious that other genetic factors should be responsible for the cystinuria phenotype in nearly 15% of patients." (PMID 30342472, 2018). "Cystinuria is associated with mutations in SLC3A1 and SLC7A9 genes." (PMID 25029527, 2014). "Two different types of cystinuria may be distinguished according to genetic: type A cystinuria, due to mutations along the SLC3A1 gene encoding the rBAT heavy subunit and type B cystinuria, with mutations in the SLC7A9 gene encoding for light subunit b0,+ AT." (PMID 25048459, 2014). "A more recent classification system has been developed, which designates patients who are homozygous for the SLC3A1 mutations as cystinuria type A, patients who are homozygous for the SLC7A9 mutations as type B, and those who have a mutation in both the SLC3A1 and SLC7A9 genes as type AB." (PMID 22857835, 2012). "In this study, we reviewed the SLC3A1 and SLC7A9 variants identified from cystinuria patients of our institute, which revealed novel variants not reported to date as well as reclassified a previously reported variant of uncertain significance as a likely pathogenic variant." (PMID 37439839, 2023). "Several non-mastiff breeds have a high frequency of the SLC7A9 variant alone (e.g., Golden Retriever, Swedish Vallhund, and English Cocker Spaniel; allele frequencies 12–26%) calling into question if the variant is a risk factor for cystinuria on its own." (PMID 36848397, 2023). "Consequently, AGT1/ SLC7A13 has been suggested as a further candidate gene for cystinuria, mutations in this factor might explain the so far unsolved cases of cystinuria in which mutations in SC3A1 and SLC7A9 had been excluded." (PMID 30342472, 2018). "However, with the exception of populations with founder mutations, the detection rate for mutations in the SLC3A1 and SLC7A9 genes never reaches 100%, and genetic variants in both genes account for 80–85% in the cystinuria population." (PMID 30342472, 2018). "Mutations in non-explored regions of SLC3A1 and SLC7A9 could be responsible for the cystinuria phenotype in these unidentified cases." (PMID 26359869, 2015).
cystinuria (continued). "Considering the observation that in many studies the detection rates for mutations in SLC3A1 or SLC7A9 do no reach 100% and due to the complex nature of renal amino acid transport, the role of further genes and modifying factors in the etiology of cystinuria have been postulated." (PMID 22480232, 2012). "The defective SLC7A9 and SLC3A1 will lead to cystinuria, characterized by defective cystine and dibasic amino acid transport across the apical membrane of epithelial cells of the small intestine and the renal proximal tubules." (PMID 39259834, 2024). "In our study, SLC3A1, SLC7A9, and SLC7A13 genes were sequenced in 34 clinically diagnosed cystinuria patients." (PMID 38138969, 2023). "With the exclusion of SLC7A13/AGT1 as the third cystinuria gene, the question remains unanswered why analysis for the two cystinuria genes SLC3A1 and SLC7A9 succeeds only in up to 85%." (PMID 30342472, 2018). "Although there was one positive test for a KSD related gene, SLC7A9 (Cystinuria), it did not change their management as they formed carbon phosphate stones and not cystine stones likely due to incomplete penetrance." (PMID 40126616, 2025). "Two genes have been identified to be involved in cystinuria formation, i.e., SLC3A1 and SLC7A9." (PMID 36421847, 2022). "The two patients with a definite diagnosis of cystinuria, due to detection of variations in the SLC3A1 and SLC7A9 genes and stone analysis suggesting l-cystine, were treated with strict alkalization urine therapy because they were too young to develop a typical staghorn stone." (PMID 35612621, 2022). "Mean HU was compared for both cystinuria genes (SLC3A1 and SLC7A9) using an independent t-test." (PMID 33169184, 2021). "We screened a cohort of 17 cystinuria patients for SLC7A13 variants which were negative for SLC3A1 and SLC7A9 mutations." (PMID 30342472, 2018). "We found that, after Slc7a9 was artificially reduced in rats, terms for membrane and transmembrane transport showed significant changes, and KEGG enrichment analysis indicated that pathways of GSH metabolism might function during cystinuria." (PMID 35416493, 2022). "It has yet to be determined if SLC7A13 mutations could help explain the isolated cystinuria observed in patients who still do not have any detectable mutation in SLC3A1 and SLC7A9." (PMID 31878022, 2019). "In human patients cystinuria is attended by mutations in SLC3A1 and SLC7A9, but it is not known whether these defects are present in carriers of HNF1β mutation." (PMID 22438943, 2012). "After identification of the molecular basis of the disease a new classification was suggested: the autosomal recessively inherited type I cystinuria which is mainly caused by SLC3A1 mutations, and the incomplete autosomal dominant non-type I cystinuria associated with SLC7A9 variants." (PMID 22480232, 2012). "However, linkage analyses in cystinuria families did not indicate the existence of more than two cystinuria loci, 2p21 (SLC3A1) and 19q13 (SLC7A9), therefore the localisation of further genes encoding amino acid transporter subunits within this region was conceivable." (PMID 22480232, 2012). "Up-regulated genes included several genes (SLC7A9, SEMG1, SBSPON and MEGF6) that were not well functionally characterized (except SLC7A9, a marker for cystinuria) and are not discussed here." (PMID 29284484, 2017). "In accordance with the functional annotation of DEGs, the potential role of glutathione metabolism processes in the kidney of cystinuria rat model was proposed, and KEGG analysis results showed that knock-out of Slc7a9 gene triggered more biological changes which has not been studied." (PMID 35416493, 2022).
nephrolithiasis (8 papers, 2012 to 2024). The presence of a calculus in the pelvis of the kidney; this is most often composed of mineral salts and proteins. "Notably, this variant and c.878T>C p.(Phe293Ser) in SLC7A9 were detected in a compound heterozygous state in patient P29, a cystic stone case who experienced recurrent nephrolithiasis three times." (PMID 37144129, 2023). "Indeed, more than 95% of all carriers of two SLC3A1 or SLC7A9 mutations (genotypes AA, BB, AB) will develop kidney stones in their live but the age of kidney stone formation is difficult to predict and shows a broad intrafamilial variability." (PMID 22480232, 2012). "Cystineuria is a rare hereditary disease associated with kidney stones, which is primarily caused by mutations in two protein subunits (rBAT and b0,+AT) encoded by SLC3A1 and SLC7A9." (PMID 33109206, 2020). "12% of double mutants (3 of 24 Slc7a9-/-Slc3a1-/- mice) showed renal calculi that filled the cavity of the renal papilla acquiring a staghorn shape, which collapsed the kidney and led to renal failure." (PMID 26359869, 2015).
breast carcinoma (3 papers, 2024 to 2025). ",15,37, 38, 39 SLC3A1, an auxiliary subunit of the rBAT–b (0,+)AT1 (SLC7A9) transporter system, is linked to the capacity of breast cancer cells to maintain their redox state by promoting the accumulation of reduced GSH, thereby decreasing lipid peroxide levels and maintaining cell survival." (PMID 39437660, 2024).
type B cystinuria (3 papers, 2015 to 2025). "To avoid sex impacts on the severity of type B cystinuria, we collected 24-h urine from 2-month-old Slc7a9-deficient and WT rats of both genders." (PMID 35416493, 2022). "The two patients with type B cystinuria carried compound heterozygous mutations in the SLC7A9 gene." (PMID 40428323, 2025).
Aminoaciduria (2 papers, 2017 to 2025). An increased concentration of an amino acid in the urine. "The review highlighted 9 genes associated with aminoacidurias, including SLC3A1 (rBAT), SLC7A9 (bo,+AT), SLC6A19 (BoAT1), SLC7A7 (y+LAT1), SLC7A6 (y+LAT2), SLC36A2 (PAT-2), SLC6A20 (SIT-1), SLC6A18 (BoAT3), and SLC1A1 (EAAT3)." (PMID 41142409, 2025).
gastric cancer (2 papers, 2024 to 2025). A primary or metastatic malignant neoplasm involving the stomach. "SLC7A9 promotes gastric cancer progression by inhibiting ferroptosis via regulation of cystine and glutamate transport, glutathione metabolism, and redox equilibrium." (PMID 39437660, 2024). "To further confirm the oncogenic role of SLC7A9 in human gastric cancer, we treated cells with erastin and evaluated the growth of the organoids." (PMID 39437660, 2024). "In conclusion, these findings confirmed that SLC7A9 drove ferroptosis resistance and that SLC7A9 knockdown sensitised gastric cancer cells to ferroptosis in vivo." (PMID 39437660, 2024). "In our previous study, SLC7A9 was identified as the most significant DRG between gastric cancer tissues and normal control tissues using DRN analysis." (PMID 39437660, 2024). "In conclusion, SLC7A9 promotes gastric cancer progression by inhibiting ferroptosis via the regulation of cystine and glutamate transport, GSH metabolism, and the redox equilibrium." (PMID 39437660, 2024). "In our previous differential regulation network (DRN) analysis of gastric cancer, SLC7A9 was identified as the most significant differentially regulated gene (DRG) between gastric cancer and adjacent tissues." (PMID 39437660, 2024). "To further confirm the role of SLC7A9 in mediating drug resistance in human gastric cancer, we established PDO models using gastric cancer tissues." (PMID 39437660, 2024). "Therefore, therapeutic interventions targeting SLC7A9 are promising for sensitising gastric cancer cells to ferroptosis, and ultimately improving the prognosis of patients with gastric cancer." (PMID 39437660, 2024). "Moreover, SLC7A9 overexpression attenuated the cytotoxic effect of erastin-induced ferroptosis of gastric cancer cells." (PMID 39437660, 2024). "A higher staining score for SLC7A9 in tumour tissues was correlated with rapid tumour recurrence (p = 0.0203, chi-square test) and an advanced TNM stage (p = 0.002, chi-square test), which indicated that SLC7A9 promoted resistance to chemotherapy and the progression of gastric cancer." (PMID 39437660, 2024). "Therefore, we plan to explore the subtypes of gastric cancer with high expression levels of SLC7A9 through multi-omics analysis." (PMID 39437660, 2024). "Therefore, therapeutic interventions targeting SLC7A9 are promising for sensitising gastric cancer cells to ferroptosis and chemotherapy treatment, and ultimately, improving the prognosis of patients with gastric cancer." (PMID 39437660, 2024). "SLC7A9 knockdown sensitised gastric cancer cells to PT and 5-FU in PDO, Allograft tumour models and PDX models, which recapitulate gastric cancer characteristics in the laboratory." (PMID 39437660, 2024). "Therefore, we speculated that SLC7A9 played a more important role in gastric cancer than SLC7A11." (PMID 39437660, 2024). "In this study, we found that the SLC7A9 expression level correlated with both GSH metabolism and ferroptosis in gastric cancer cells." (PMID 39437660, 2024). "According to the metabolome and transcriptome data, SLC7A9 is mainly involved in GSH metabolism and ferroptosis in gastric cancer cell lines." (PMID 39437660, 2024).
gastric cancer (continued). "Although the expression level of SLC7A9 is higher in gastric cancer than in normal tissue, there is a lack of appropriate methods to downregulating its expression." (PMID 39437660, 2024). "In addition, we plan to design anti-SLC7A9 and anti-SLC7A11 antibody-drug conjugates in a follow-up study, to improve drug targeting of gastric cancer." (PMID 39437660, 2024). "SLC7A9 knockdown reduced cystine transport into cells, hampered intracellular cystine and GSH metabolic flow, decreased GSH synthesis, and increased lipid ROS levels in gastric cancer cells." (PMID 39437660, 2024). "In our previous study, DRN analysis showed that SLC7A9, but not SLC7A11, was a key regulator in gastric cancer." (PMID 39437660, 2024).
kidney failure (2 papers, 2014 to 2015). An acute or chronic condition that is characterized by the inability of the kidneys to adequately filter the blood. "Furthermore, we found urine lysine concentration to be associated with SNPs in the SLC7A9 gene, which is linked to kidney function and to kidney failure specifically." (PMID 24586186, 2014).
Obesity (2 papers, 2018 to 2024). Accumulation of substantial excess body fat. "Lower expression of amino acid transporters, including SLC7A9, has been observed in hepatocytes from mice with diet-induced obesity, and this decrease was associated with hepatic steatosis, hyperlipidemia, obesity, and IR." (PMID 38422035, 2024). "In line with obesity-associated upregulation of Slc7a9, an amino acid transporter, targeted metabolomics analysis revealed significant increases in the levels of most amino acids in the colonic epithelium of young obese mice, reminiscent of a metabolic trait observed in human colon cancer." (PMID 29346762, 2018).